CD34 (CD34 molecule)
Diseases named in the same sentence as CD34 in open-access papers (continued):
Sharing a sentence is not in itself a finding about the gene and the disease.
chronic kidney disease (11 papers, 2017 to 2024). Impairment of the renal function secondary to chronic kidney damage persisting for three or more months. "The effectiveness of CD34+ EPC therapy on the protection of CKD (chronic kidney disease) renal function has only been documented in a small number of experimental investigations." (PMID 37138792, 2023). "The STEMI patient with Killip-3 upon presentation at the time interval after 12 months of CD34+ cell therapy developed end-stage renal disease on regular hemodialysis after primary coronary intervention mainly due to contrast media-induced nephrotoxicity." (PMID 28148896, 2017). "This was a phase I clinical trial to investigate the safety of autologous peripheral-blood-derived CD34+ cell therapy for patients with chronic kidney disease (CKD-treatment) (i.e., at Stages III and IV)." (PMID 28148896, 2017).
chronic myelomonocytic leukemia (11 papers, 2016 to 2026). A myelodysplastic/myeloproliferative neoplasm which is characterized by persistent monocytosis, absence of a Philadelphia chromosome and BCR/ABL fusion gene, fewer than 20 percent blasts in the bone marrow and blood, myelodysplasia, and absence of PDGFRA or PDGFRB rearrangement. "TET2 mutations were subsequently identified in CD34‐positive progenitor cells in patients with MDS and chronic myelomonocytic leukemia (CMML), suggesting an early clonal origin." (PMID 40116537, 2025). "In patients who develop chronic myelomonocytic leukemia and carry TET2 mutations in CD34+ hematopoietic progenitor cells, the TET2-mutated CD34+ progenitors preferentially develop into myeloid instead of erythroid cells upon differentiation." (PMID 30290828, 2018). "RNA-Seq investigation of CD34+ bone marrow cells from MDS or chronic myelomonocytic leukemia (CMML) patients revealed an overexpression of the necroptotic executor MLKL and its relationship with anemia severity." (PMID 38730609, 2024). "A trial which included 124 bone marrow biopsies from patients with MDS, AML and chronic myelomonocytic leukemia (CMML) showed that PD-1, PD-L1, PD-L2 and CTLA4 were upregulated in CD34+ cells." (PMID 33804850, 2021). "Here, we showed that BMSCs derived from chronic myelomonocytic leukemia patients had reduced expression of ASXL1, which impaired the maintaining cord blood CD34+ cell colony-forming capacity with a myeloid differentiation bias." (PMID 29423272, 2018). "We evaluated the expression of BCL2 in bone marrow CD34+ cells from a cohort of MDS and chronic myelomonocytic leukemia patients with and without ASXL1 mutations." (PMID 34548471, 2021).
leukocytosis (11 papers, 2012 to 2025). "During its development, treatment with this drug was noted to induce leukocytosis and increase the number of CD34 positive cells in the peripheral circulation." (PMID 28628632, 2017). "In this patient, the diagnosis of de novo AML with mutated NPM1 was made on his first bone marrow biopsy showing 70% CD13, CD33, CD117, HLA-DR(+), and CD34(−) myeloblasts with circulating blasts and marked leukocytosis." (PMID 27752371, 2016). "Presence of JAK2V617F mutation correlated with a reduced level of thrombocytosis in ET and increased absolute number of circulating CD34+ cells, leukocytosis, and erythrocytosis in patients with PV." (PMID 26491227, 2015). "Cases with FLT3-ITD presented a microgranular morphology, PB leukocytosis and expression of HLA-DR, CD34 and CD11b." (PMID 22742960, 2012). "Moreover, both the research findings and available literature have shown an association between leukocytosis and CD2, CD34, and CD56 expression." (PMID 25045197, 2014). "This CD34+ CD38− phenotype as well as other factors such as tumor syndrome, high leukocytosis and blasts are considered as important factors of poor prognosis." (PMID 23667721, 2013). "Three dogs presented with a marked leukocytosis (range: 27,130–514,620 leukocytes/μL), no or moderate peripheral lymphadenopathy and an expanded population of intermediate to large CD34+ cells on blood FCM." (PMID 41394920, 2025). "Additionally, there were significantly more cases of bone marrow involvement, hepatic involvement, leukocytosis > 100 × 109/L, hemoglobin level < 12 g/dL, platelet count < 100 × 109/L, LDH elevation above the normal range, CD34 positivity, and allo‐HSCT in the T‐ALL group than in the T‐LBL group." (PMID 41388921, 2025). "Nonetheless, both CD2+ and CD34+ immunophenotypes are associated with leukocytosis, so differences in clinical outcomes between patients with CD2+ APL and CD2− APL or CD34+ APL and CD34− APL may be due to WBC counts and not because of CD2+ or CD34+ expression." (PMID 25045197, 2014). "CD34+ CD38− phenotype is found in all patients regardless of value and presented poor prognosis factors such as leukocytosis, blasts." (PMID 23667721, 2013).
lymphangioma (11 papers, 2007 to 2026). A benign lesion composed of dilated lymphatic channels. "In lymphangiomas, endothelial markers such as CD34, CD31, Factor VIII, and VEGFR3 are typically positive.7) In the present case, cuboidal cells were observed, suggesting a tumor of mesothelial origin." (PMID 41024978, 2025). "Immunohistochemistry can aid in further distinguishing this tumor: both vascular and lymphatic endothelial cells express CD31 and CD34, whereas D2-40 is expressed only in lymphangioma and some malignant vascular tumors." (PMID 40018410, 2025). "Immunoelectron microscopic studies have demonstrated up-regulation of CD31 and CD34 and show type IV collagen expression in lymphangiomas." (PMID 17584927, 2007). "Immunohistochemically, D2-40 is a specific marker for lymphangioma, while CD31, CD34, von Willebrand factor, and VEGFR3 can also be helpful for diagnosis." (PMID 39411124, 2024). "To prove the lymphatic origin of the endothelial cells of cysts, we performed immunohistochemical analysis using a representative set of markers consisting of CD31, factor VIII-related antigen, D2-40, CD34, AE1/AE3, and calretinin for the diagnosis of lymphangioma." (PMID 31651341, 2019).
metastatic tumors (11 papers, 2011 to 2025). "CD34 immunohistochemistry also showed that the microvascular density of the metastatic tumors in the Ts-exo group was significantly higher than that in the Nc-exo group." (PMID 38532427, 2024). "In the current case, the tumor was not only a metastatic disease but also histopathologically exhibited a high mitotic rate (10 mitoses per 10 high-power fields) and sparse staining for CD34, indicating its malignant potential." (PMID 31520184, 2019). "In our study, we further found that the high protein expression of CD31 and CD34 (angiogenesis markers) was consistent with the high protein expression of COL10A1 in the peritoneal metastatic tumors of GC patients." (PMID 30154451, 2018). "Next, we detected the protein expressions of cell proliferation (Ki-67) and angiogenesis (CD31 and CD34) markers in the peritoneal metastatic tumors." (PMID 30154451, 2018). "Given the role of angiogenesis in RCC, the area of CD-34 expressing cells within the tumor mask was measured in both the primary and metastatic tumors of 34 patients." (PMID 23316728, 2013). "Furthermore, we detected the protein expression of SOX9, COL10A1, Ki-67 (cell proliferation marker), CD31 and CD34 (angiogenesis markers) in peritoneal metastatic tumors of GC patients." (PMID 30154451, 2018). "Similarly, in animals treated with hepatic RFA alone, metastatic tumors demonstrated increased cellular proliferation (Ki-67) and microvascular density (CD34) compared to sham, sham plus atorvastatin, and RFA plus atorvastatin (p-value <0.001, all comparisons)." (PMID 35857766, 2022). "Immunohistochemical staining yielded positive results for ERG, CD31, CD34 and CD117, and echocardiography identified a large tricuspid valve mass, suggesting metastatic disease." (PMID 40900681, 2025). "We found that even advanced fibrosis is not an absolute barrier to metastatic disease, particularly if portal circulation is intact and if sinusoidal capillarization, as demonstrated by negative CD34 imunostains, is absent." (PMID 33639984, 2021). "Resection of the metastatic tumors had revealed that CD-34 was totally absent in the tumors." (PMID 27239363, 2016). "CD34-indexT and CD34-indexTN did not correlate with age (p = 0.543), sex (p = 0.225), treatment (p = 0.848), International mRCC Database Consortium category (p = 0.152), synchronous versus metachronous metastatic disease (p = 0.378), or tumour volume (p = 0.848)." (PMID 34327591, 2021).
neural tumors (11 papers, 2010 to 2025). "The dual expression of S100 and CD34 in immunohistochemistry should raise strong suspicion of lipofibromatosis-like neural tumors, and NTRK gene testing can be a valuable tool for differential diagnosis." (PMID 39345656, 2024). "Although OFM lacks specific immunohistochemical markers, IHC is useful for excluding other myxoid lesions—S-100 helps rule out neural tumours, while CD34, STAT6, and BCL2 assist in excluding myxoid solitary fibrous tumour." (PMID 41283480, 2025). "However, if they do not show positive immunoreactivity or if there is difficulty in differentiation between different neural tumours we can apply other staining tests like epithelial membrane antigen (EMA), factor XIIIa, CD34 or CD68, or type IV collagen." (PMID 25478247, 2014).
non-small cell lung carcinoma (11 papers, 2002 to 2026). A group of at least three distinct histological types of lung cancer, including non-small cell squamous cell carcinoma, adenocarcinoma, and large cell carcinoma. "In non-small cell lung cancer, MPP showed a significant inverse association with CD34 expression, which is an immunohistochemial marker of angiogenesis." (PMID 34354986, 2021). "In a non-small cell lung cancer (NSCLC) stem-like cell line (H1650 CD133(+) CD34(–) cells), researchers have found that miR-27a has higher expression in H1650 CSCs and regulates cancer development in H1650 cells." (PMID 31572683, 2019). "Immunohistochemical analysis of 141 resected non-small cell lung cancers showed tumor cell expression of CD44 in 50.4% of tumors while no CD34, and CD133 expression was observed in tumor cells." (PMID 21124918, 2010). "In addition, this tumor frequently displays the robust expression of one or more stem cell markers, such as SOX2, CD34, and SALL4, which can facilitate the differential diagnosis of SMARCA4-deficient non-small cell lung cancer (NSCLC) (SMARCA4-dNSCLC), typically negative for these markers." (PMID 38881888, 2024).
osteoarthritis (11 papers, 2006 to 2025). A noninflammatory degenerative joint disease occurring chiefly in older persons, characterized by degeneration of the articular cartilage, hypertrophy of bone at the margins and changes in the synovial membrane. "Despite some controversy in the literature regarding expression of CD34 by AD-MSCs, a recent study examining MSCs used to treat osteoarthritis showed that MSCs increased expressed CD34 under chronic inflammation." (PMID 40468129, 2025). "The purpose of this study was to evaluate the effectiveness of physiotherapy after the implantation of CD34+ stem cells into the hip joints of patients with osteoarthrosis." (PMID 39728039, 2024). "Allanore and colleagues found increased levels of CD34+/CD133+ cells in SSc as compared to osteoarthritis patients." (PMID 27519706, 2016). "CD34+ cells were purified from bone marrow samples obtained from 49 RA patients and 31 osteoarthritis (OA) patients during joint operations via aspiration from the iliac crest." (PMID 16519794, 2006). "In this regard, it is worth mentioning that a previous work noticed an expansion of a fibroblast population expressing podoplanin, CD90/Thy1 and cadherin‐11, but lacking CD34, in patients with RA relative to patients with osteoarthritis." (PMID 33350073, 2021). "Freshly isolated cells from muscle from patients with osteoarthritis showed a lower proportion of CD45/CD19/CD14/CD34-negative cells compared to patients with osteoporosis and healthy donors." (PMID 32245507, 2020). "One fibroblast subset, characterized by the expression of proteins podoplanin, THY1 membrane glycoprotein and cadherin-11, but lacking CD34, is threefold expanded in patients with RA relative to patients with osteoarthritis." (PMID 29476097, 2018). "The presence of CD34+KDR+ cells was previously shown also in the synovial tissue of patients with RA and osteoarthritis, indicating that this is not a specific finding in JIA." (PMID 25925313, 2015).
systemic sclerosis (11 papers, 2010 to 2025). A chronic disorder, possibly autoimmune, marked by excessive production of collagen which results in hardening and thickening of body tissues. "In systemic sclerosis (scleroderma), in which a derangement of the microvascular system occurs, a progressive reduction and loss of CD34+SCs/TCs has been described in the dermal cellular network." (PMID 34298962, 2021). "The abundant CD34+ dermal fibroblasts present in healthy human skin are lost in the skin of patients with systemic sclerosis, and CD34−, podoplanin+, and CD90+ fibroblasts are present." (PMID 36747131, 2023). "These two pathways indicated that T cell was differentiated to Th1 subset after AHST, which was consistent with a recent study displaying predominant reconstitution of Th1 CD4+T after autologous CD34+ stem cell transplantation in patients with systemic sclerosis." (PMID 22384093, 2012). "The effectiveness of autologous haematopoietic stem cell transplantation (auto-HSCT) in treating severe systemic sclerosis (SSc) is established; however, the necessity of purified CD34+ cell grafts and the appropriate conditioning regimen remain unclear." (PMID 30670057, 2019). "For patients with systemic sclerosis treated with HCT, TRM is considered to be related with the transplant regimen and, thus, cardiotoxicity, the optimal regimen for mobilization and conditioning, the selection or not of CD34 + graft, and the lack of unanimous HCT eligibility criteria." (PMID 40727525, 2025).
cerebral infarction (10 papers, 2011 to 2025). An ischemic condition of the brain, producing a persistent focal neurological deficit in the area of distribution of the cerebral arteries. "Among patients with a history of atherothrombotic cerebral ischemic events, a strong inverse association between circulating CD34-positive cells and the number of cerebral infarcts was reported." (PMID 35159980, 2022). "In addition, a previous study with a history of atherothrombotic cerebral ischemic events reported a strong inverse association between circulating CD34-positive cells and the number of cerebral infarcts." (PMID 33549053, 2021). "The expression of the adhesion molecule integrin β2 (CD18) in CD34-positive (CD34+) cells was identified as critical for the therapeutic effect on cerebral infarction in a murine model." (PMID 40003604, 2025). "Growing preclinical studies have shown that either intravenous or intracarotid artery administration of CD34 + effectively reduced the brain infarct volume and preserved the neurological function in both acute IS and chronic IS animal models." (PMID 39568005, 2024). "Thereafter, the cerebral infarction volume, neurological function, and the expression level of CD34, an angiogenesis marker, was analyzed in CIRI rats by TTC staining, neurological defect score and WB." (PMID 36108080, 2022). "In the current study, we observed that G-CSF administration, leukapheresis, and intrathecal administration of CD34 positive cells were safe and well tolerated in a group of patients with past cerebral infarction with 12-month followup." (PMID 24187628, 2013). "In the current study, patients with past cerebral infarction were treated by G-CSF; subsequently, leukapheresis was performed for CD34 positive cells collection by immunoselection." (PMID 24187628, 2013). "Increasing evidence shows that circulating CD34+ cells contribute to angiogenesis after brain infarction." (PMID 21887230, 2011). "In this study, we focused on an adhesion molecule expressed in CD34+ cells and examined whether the expression level of integrin β2 (CD18) is associated with the efficacy of cell transplantation therapy for cerebral infarction." (PMID 40003604, 2025).